CD99 (CD99 molecule (Xg blood group))
Diseases named in the same sentence as CD99 in open-access papers (continued):
Sharing a sentence is not in itself a finding about the gene and the disease.
glioma (11 papers, 2016 to 2025). A benign or malignant brain and spinal cord tumor that arises from glial cells (astrocytes, oligodendrocytes, ependymal cells). "In human glioma cells over-expression of CD99 is implicated in MAT, resulting in rounded morphology, increased Rho activity, and enhanced migration." (PMID 32245408, 2020). "CD44 and CD99 have been implicated in increasing the invasion potential of glioma cells, and were also increased in the EVs of irradiated T98G cells." (PMID 32033611, 2020). "A recent bioinformatic analysis from multiple gliomas datasets highlighted an association of CD99 overexpression with tumor hypoxia, angiogenesis, epithelial-mesenchymal transition, metabolic reprogramming, and an immunosuppressive microenvironment dominated by M2 tumor-associated macrophages." (PMID 38607036, 2024). "Conversely, the ectopic expression of CD99 in glioma cells resulted in increased cell migration and invasiveness." (PMID 40427525, 2025). "A bioinformatic analysis of multiple glioma datasets identified CD99 as a biomarker that characterizes the adaptive response." (PMID 40427525, 2025). "High CD99-expressing gliomas tolerate stress conditions like hypoxia and antitumor immunity, affecting responses to anti-angiogenic and immune checkpoint inhibitors." (PMID 40427525, 2025). "This links to reduced Rac and increased Rho activity, leading to more amoeboid than mesenchymal cells, highlighting CD99’s role in the amoeboid–mesenchymal transition during glioma migration." (PMID 40427525, 2025). "CD99 expression levels are found to be elevated in GBM compared to normal brain tissue or lower-grade gliomas." (PMID 40427525, 2025). "The same study found an upregulation of the PI3K-AKT pathway in gliomas with CD99 overexpression and a potential sensitivity to inhibitors of this pathway." (PMID 38607036, 2024). "Orthotopic xenografts of glioma cell lines overexpressing CD99 developed tumors with wider spread and indistinct margins and had significantly reduced survival compared with xenografts not expressing CD99." (PMID 38607036, 2024). "To further understand this potentiality, we analyzed the differential expression of its two isoforms in human astrocytoma specimens, and the CD99 involved signaling pathways in glioma model U87MG cell line." (PMID 30845661, 2019). "Nonetheless, glioma U87MG cells over-expressing CD99 have presented a higher proportion of amoeboid migration, with high cortical tension and low adhesion to ECM, than that in control cells." (PMID 30845661, 2019). "In this research, the specificity of miR210HG in glioma diagnosis was better than that offered by the CD99 test." (PMID 27673330, 2016). "This phenotype was associated with decreased Rac activity and increased Rho activity along with a significantly increased proportion of amoeboid cells to mesenchymal cells, suggesting the involvement of CD99 in amoeboid–mesenchymal transition in glioma migration." (PMID 40427525, 2025). "Therefore, for patients with CD99-overexpressing gliomas, it is essential to consider tumor adaptiveness during treatment to prevent drug resistance, and closer clinical monitoring should be conducted to improve the effectiveness of treatment." (PMID 40427525, 2025). "Furthermore, glioma patients with high CD99 expression exhibited resistance to chemotherapy and radiotherapy, and a positive correlation was found between increased CD99 levels and poor short-term recurrence and survival." (PMID 40427525, 2025). "CD99 also regulated the adhesion of glioma cells to laminin." (PMID 40427525, 2025). "The prognostic impact of CD99 expression emerged only when considering gliomas of all grades." (PMID 40427525, 2025). "It has been demonstrated that suppressing CD99 expression by interfering RNA in glioma tumour cell lines markedly reduced cell migration, further suggesting that CD99 may contribute to the infiltrative ability of tumour cells." (PMID 33686173, 2021).
glioma (continued). "Additionally, previous microarray expression analyses in gliomas have revealed CD99 among 31 genes coding for membrane proteins potentially targetable for immunotherapy." (PMID 30845661, 2019). "It would be useful to identify whether combining the miR210HG content and values of CD99 could enhance the sensitivity and specificity of glioma diagnosis." (PMID 27673330, 2016). "Our cophenetic correlation coefficient calculations (CCC) are in support of EMMPRIN/CD147, CD99, Cathepsin D, Intβ1, ADAM9/-17, and Galectin-3 being suitable biomarkers for glioma cells and potentially, SLGCs." (PMID 38306361, 2024). "Seol HJ and colleagues confirmed that gliomas exhibit elevated CD99 expression compared to non-neoplastic brain tissue and that silencing CD99 in glioma cells reduces migration and invasiveness without affecting cell viability or proliferation." (PMID 40427525, 2025). "The CD99 test in glioma patients has a high sensitivity without enough specificity because CD99 is also present in patients with other cancers, such as gastric cancer." (PMID 27673330, 2016).
myelodysplastic syndrome (9 papers, 2018 to 2025). A clonal hematopoietic disorder characterized by dysplasia and ineffective hematopoiesis in one or more of the hematopoietic cell lines. "We then measured the expression of another stem cell marker, CD99, which is a marker of acute myeloid leukaemia (AML) and myelodysplastic syndrome (MDS) stem cells." (PMID 37648998, 2023).
autoimmune disease (8 papers, 2016 to 2025). A disorder resulting from loss of function or tissue destruction of an organ or multiple organs, arising from humoral or cellular immune responses of the individual to their own tissue constituents. "In conclusion, despite the divergent effects of CD99 on the immune responses, the insights coming from the human autoimmune diseases and animal models of autoimmune diseases, support the pathologic roles of CD99 in autoimmunity." (PMID 33297945, 2020). "The expression and function of the CD99 molecule in immune cells may suggest its involvement in the etiopathogenesis of certain autoimmune diseases." (PMID 40427525, 2025). "All these findings suggest that CD99 is a promising target for treating autoimmune diseases." (PMID 40427525, 2025). "Sex-specific differential surface expression of CD99 on T cells and pDCs could possibly contribute to higher female preponderance in autoimmune diseases." (PMID 38750588, 2024). "The data suggest that dysregulation of CD99 and CSF2RA might underlie the increased frequency of autoimmune diseases in females with TS." (PMID 32210915, 2020). "Hence, differential CD99 expression is not regulated in this autoimmune disease in the peripheral blood, but could still mediate functional differences of T cells and pDCs with relevance for the disease pathogenesis and perpetuation." (PMID 38750588, 2024).
COVID-19 (7 papers, 2022 to 2024). A disease caused by infection with severe acute respiratory syndrome coronavirus 2. "Recently, deregulation of CD99 antigen peptides were implicated in COVID-19-associated kidney injury and CKD in different studies." (PMID 37930730, 2024). "At the same time, it becomes evident that specific changes, a decrease of peptides from CD99 antigen, are associated more specifically with critical COVID-19, and cannot be consistently associated with all-cause death, neither in nor outside ICU." (PMID 37741989, 2023). "The most prominent difference in comparison to the distribution in COVID-19 patients was observed for peptides derived from CD99 antigen and polymeric immunoglobulin receptor." (PMID 37741989, 2023). "This suggests that the “second hit” in the context of a SARS-CoV-2 infection is depicted via peptides deregulated in severe COVID-19 only, like CD99 antigen." (PMID 37741989, 2023). "Additionally, the association of microRNA 125b with CD99 and CD11b was strongly affected in AML patients infected by COVID-19." (PMID 38902412, 2024). "Also, a consistent reduction in CD99 was observed in severe cases of COVID-19, where a significant reduction in CD99 also was found on the surface of peripheral blood lymphocytes." (PMID 39335603, 2024). "Based on the data, the authors hypothesized that reduction in CD99 may have a negative impact on the endothelial barrier integrity, a well-known phenomenon in severe COVID-19." (PMID 39335603, 2024). "On the other side, CD99 signaling in the NK cells and CADM1 signaling in the CD8+ TCM were observed in the COVID-19 patients but not in healthy or recovered individuals." (PMID 36532041, 2022).
gastric cancer (7 papers, 2010 to 2023). A primary or metastatic malignant neoplasm involving the stomach. "In gastric cancer, CD99 is present in normal gastric epithelium and its levels decrease in less differentiated tumors." (PMID 29305692, 2018). "KCMF1 has been reported to be down-regulated in Ewing’s sarcoma cell lines after the over expression of CD99 and up-regulated in gastric cancer (KCMF1 as a CD99-regulated putative metastasis suppressor gene)." (PMID 25563226, 2014). "In other tumors, such as Hodgkin lymphoma, OS, prostate cancer and gastric cancer, CD99 is expressed at low levels and the downregulation of CD99 rather than its over-expression seems to be required for tumorigenesis." (PMID 29305692, 2018).
hemangiopericytoma (7 papers, 2010 to 2018). An antiquated term that refers to benign or malignant mesenchymal neoplasms characterized by the presence of neoplastic spindle-shaped to round cells arranged around thin-walled branching vascular spaces. "The histopathologic examination and immunohistochemistry staining results (positive for CD34, CD31 and smooth muscle actin, but negative for CD99, S100, B-cell lymphoma 2 (bcl-2) and desmin) confirmed the diagnosis of hemangiopericytoma." (PMID 29785407, 2018). "The diagnosis of hemangiopericytoma was excluded because there were no typical spider-like radial branching vessels nor collagen IV and CD99 positivity." (PMID 20573206, 2010).
prostate carcinoma (7 papers, 2008 to 2025). A carcinoma that arises from epithelial cells of the prostate gland. "In fact, the overexpression of CD99 in prostate cancer cells inhibited their migration and metastatic potential in both in vitro and in vivo experiments." (PMID 35267445, 2022). "Formalin-fixed paraffin-embedded prostatic cancers were stained with NKp30-Ig, NKp46D2-Ig or the control fusion proteins (such as CD99-Ig)." (PMID 18478075, 2008). "The human prostate cancer cell line PC3 is also used to analyse cancer cell TEM and metastatic pathways; this cell line expresses CD99 and, upon CD99 depletion, also demonstrates increased spreading on an EC monolayer." (PMID 34374417, 2021).
Wilms tumor (7 papers, 2012 to 2025). An embryonal neoplasm characterized by the presence of epithelial, mesenchymal, and blastema components. "In addition, immunohistochemical staining was performed on Sertoli cells for Wilms' Tumor, Melan-A, and CD99 to evaluate histopathological changes." (PMID 34567182, 2021). "Wilms tumors usually strongly express WT1 and fail to express membranous CD99, FLI-1, or nuclear NKX2.2." (PMID 40978053, 2025).
mesenchymal tumors (6 papers, 2011 to 2024). "Specifically, CD99 is a highly sensitive and useful immunohistochemical marker for ES, usually showing a diffuse, strong, membranous pattern of distribution, but it is expressed within a broad variety of mesenchymal tumors as well." (PMID 32225029, 2020). "Thus, it would be interesting to investigate whether BEND2-rearranged mesenchymal tumors do express CD99 and its functional role." (PMID 38339014, 2024). "In addition, several mesenchymal tumors have been reported to express both CD99 and bcl-2." (PMID 37315497, 2023). "Positive immunoreactivity for CD34 and CD99 is characteristic of SFT, and highly valuable in differentiating from other mesenchymal tumors." (PMID 21970525, 2011).
small cell carcinoma (6 papers, 2013 to 2025). A neuroendocrine carcinoma composed of small malignant cells which are often said to resemble "oat cells" under the microscope. "However, it has also been reported that CD99 is expressed in small-cell carcinoma, Wilms’ blastoma, and non-Hodgkin lymphoma." (PMID 37151856, 2023). "Hence, a wider range of immunohistochemical markers, including chromogranin and TTF-1 to support a diagnosis of small cell carcinoma, and CD99, vimentin, or FLI1 for PNET should be used for the differential diagnosis." (PMID 25475214, 2014).
Hodgkins lymphoma (5 papers, 2015 to 2022). A heterogeneous group of malignant lymphoid neoplasms of B-cell origin characterized histologically by the presence of Hodgkin and Reed-Sternberg (HRS) cells in the vast majority of cases. "It has also been shown that CD99 downregulation leads to the loss of normal morphology in Hodgkin’s disease, while the upregulation of CD99 in Hodgkin/Reed–Sternberg cells induces terminal B cell differentiation." (PMID 29534016, 2018). "In contrast, CD99 upregulation induces differentiation of Hodgkin lymphoma cells into terminal B-cells." (PMID 29305692, 2018).
malignant glioma (5 papers, 2019 to 2025). A grade III or grade IV glioma arising from the central nervous system. "In GBM and malignant gliomas, CD99 expression is higher in undifferentiated tumors, affecting actin dynamics and motility." (PMID 40427525, 2025). "CD99 has a controversial mechanism of action but is emerging as a novel therapeutic target particularly in malignant glioma." (PMID 37637064, 2023). "CD99 is a glycosylated transmembrane protein frequently highly expressed in malignant glioma with marked effects on the migration, invasion and metastasis of tumor cells." (PMID 34066132, 2021).
mesenchymal chondrosarcoma (5 papers, 2013 to 2024). A morphologic variant of chondrosarcoma arising from bone and soft tissue. "Of the tumors reclassified as mesenchymal chondrosarcomas (cases 14 and 16), CD99 was strongly positive in case 14, while SATB2, BCOR, and MUC4 were negative." (PMID 38332052, 2024). "Diagnosis of mesenchymal chondrosarcoma was confirmed with small foci of chondroid material and strong positivity of tumoral cells for CD99 and S100." (PMID 39503009, 2024).
pancreatic cancer (5 papers, 2021 to 2025). "Recent attention has focused on the diagnostic value of CD99 and LEF1 in distinguishing SPNs from other pancreatic neoplasms." (PMID 40307756, 2025).
thymoma (5 papers, 2007 to 2020). A neoplasm arising from the epithelial cells of the thymus. "Overall, the three specific proteins markers of immature T lymphocytes, namely TdT, CD1a, and CD99, were found at significantly higher level in type B thymoma than in type A (P < 0.05)." (PMID 31967407, 2020). "For example, although CD99 was found to have higher level in type B thymoma than in type A thymoma, it also showed high levels in normal thymus as well as in a variety of other cell lines and tissues." (PMID 31967407, 2020). "Recently, WHO had suggested a dozen of histochemical markers to differentiate type A and type B thymoma, including TdT, CD1a, CD99, PSMB11 (Beta5T), PRSS16, Cathepsin V, and desmin." (PMID 31967407, 2020). "CNOT2, CNOT9, CD99, PRSS16, PSMB11, and SHMT1 were found with high abundance in thymoma and participated mainly in nucleic acid and amino acid metabolism." (PMID 31967407, 2020). "The pattern of CD99 and TdT immunostaining was similar to that of CD1α, CD3 and CD5 in type AB thymoma and squamous cell carcinoma." (PMID 28095872, 2017). "Small stromal lymphoid aggregates containing mature T lymphocytes (CD3+, CD5+, CD1a-, CD99-, Ki67 proliferation index <10%) and CD20+ B lymphocytes were observed in all B2 and B3 thymomas." (PMID 17498299, 2007). "The inverse relation between CD99 expression and differentiation has also been confirmed in thymic tumors, in which CD99 is useful for identifying immature T cells and for distinguishing thymoma from thymic and non-thymic carcinomas." (PMID 29534016, 2018). "Type B2 and B3 thymomas showed a similar immunophenotype with a variable CK7 expression, and immature intratumoral non-neoplastic T lymphocytes (CD3+, CD5+, CD1a+, CD99+; Ki67 proliferation index >80%)." (PMID 17498299, 2007). "Similar to thymomas, mediastinal neuroendocrine neoplasms express CD57 and other neuroendocrine markers but are consistently negative for non-neoplastic immature lymphocytes (CD1a+, CD99+)." (PMID 17498299, 2007).
Astrocytoma (4 papers, 2013 to 2024). "In the present study, we examined the molecular mechanisms related to CD99 in astrocytomas, especially in GBM, based on human tumor samples and an in vitro cellular model." (PMID 30845661, 2019). "In conclusion, the present study showed that isoform 1, of CD99, is exclusively present in human astrocytomas and the U87MG cell line and regulates functions, such as cytoskeleton remodeling, cell migration, invasion, and adhesion." (PMID 30845661, 2019). "CD99 is a transmembrane protein overexpressed in several malignancies, including astrocytomas of different malignant grades, which might impact on migration and invasiveness of cancer cells." (PMID 38306361, 2024).
bone tumor (4 papers, 2016 to 2022). "The transmembrane glycoprotein CD99, or MIC2, is an important player in the oncogenesis of Ewing sarcoma (EWS), the second most common bone tumour of children and young adults." (PMID 31569680, 2019).
cervical cancer (4 papers, 2019 to 2025). A primary or metastatic malignant neoplasm involving the cervix. "Notably, the CD99 signaling pathway corresponds to Tumor EPCs pattern 1 and is secreted by almost all cell types in cervical cancer, signifying its crucial role as a significant signaling pathway." (PMID 38482016, 2024). "The upregulated ligand receptor pairs in the cervical cancer group were SPP1 − CD44, FN1 − SDC4, FN1 − SDC1, FN1 − CD44, CD99 − CD99, and the downregulated ligand receptor pairs were PPIA – BSG, LGALS9 − P4HB, LGALS9 − CD44." (PMID 41384115, 2025).
granulosa cell tumor (4 papers, 2013 to 2023). A slow-growing, malignant tumor, characterize by the presence of granulosa-like cells and Call-Exner bodies, that is almost always found in the ovary. "Luteinized granulosa cell tumor shows varying presence of nuclear grooves with vimentin, inhibin, calretinin, CD99, and SMA positivity with variable immunoreactivity for desmin and PanCK and negativity with EMA." (PMID 27818820, 2016).
meningioma (4 papers, 2012 to 2024). A generally slow growing tumor attached to the dura mater. "Immunohistochemically, HPCs typically express markers such as CD34, vimentin, CD99, and Bcl-2 while being negative for S100, which helps differentiate them from other spindle cell neoplasms like schwannomas or meningiomas." (PMID 39371697, 2024). "Glial fibrillary acidic protein, CD99, CD34, S-100 protein, neuron specific enolase, neurofilament, cytokeratin, cytokeratin 19, and Bcl-2 were negative in MA and meningioma area." (PMID 23198201, 2012).
soft tissue tumors (4 papers, 2008 to 2025). "□ Synovial Sarcoma: Most cases express CD99, BCL-2, and TLE1 proteins, with molecular genetic analysis serving as a critical tool for distinguishing it from other soft tissue tumors." (PMID 40308487, 2025). "There are many tumours in the small round cell family showing positive CD99 and PNET as one of the members of the small round cell tumour family should be considered a differential diagnosis in case of any soft tissue tumour." (PMID 35633271, 2022). "Additionally, various molecular markers, such as CD99, BCL-2, and EMA, may help differentiate SS from other soft tissue tumours." (PMID 40391194, 2025). "CD99 is not required for GIST diagnosis, but as its immunoreactivity is not uncommon in a variety of soft tissue tumors, correlation of expression of this marker with that of other immunomarkers and with morphology is warranted." (PMID 18986537, 2008).